TLR4 (toll like receptor 4)
Diseases named in the same sentence as TLR4 in open-access papers (continued):
Sharing a sentence is not in itself a finding about the gene and the disease.
neurological disorders (52 papers, 2012 to 2026). "TLR-4/NF-κB pathway activation is implicated in neuroinflammation across various neurological disorders." (PMID 41001132, 2025). "Recent research has shown that phytochemicals in food can protect neurons from neurological diseases caused by the NLRP3 inflammasome by blocking the TLR4 axis pathway signaling pathway." (PMID 36015156, 2022). "TLR4 is widely expressed in the nervous system (i.e., neurons, astrocytes, and microglia) and is implicated in various neurological disorders." (PMID 36619717, 2022). "Activation and inflammatory responses of microglia are usually associated with TLR4/NF-κB signaling pathways, which in turn trigger a range of neurological diseases, such as hypothalamic inflammation, brain injury and idiopathic Parkinson’s disease (IPD)." (PMID 31957804, 2020). "The TLR4 pathway is prominent in many neurological disorders associated with neuroinflammation." (PMID 36293468, 2022). "Our data could have important implications for understanding the complex interplay between NOD2- and TLR4-mediated inflammatory pathways in microglia, which is relevant for many neurological diseases associated with dysregulated microglial neuroinflammatory responses." (PMID 39519307, 2024). "Recent studies have highlighted the function of TLR4 as a mediator of cellular pro-inflammatory responses triggered by SD and other neurological disorders." (PMID 39830563, 2024). "EVs derived from the periodontopathogen Aggregatibacter actinomycetemcomitans can alleviate neurological diseases by downregulating the TLR4/MyD88 signaling pathway and reducing the expression of pro-inflammatory cytokines." (PMID 39472001, 2024). "Several neurological diseases are known to be associated with microglia-driven inflammation, in which NOD2 and/or TLR4/myeloid differentiation primary response protein 88 (MyD88) signaling pathways are actively involved." (PMID 39519307, 2024). "MiR-216a-5p/TLR4/NF-κB pathway participates in cell apoptosis and inflammation in various neurological disorders." (PMID 37766965, 2023). "A recent systematic review concluded that most polyphenols from plant sources can modulate microglial polarization via the TLR4/NF-κB pathway, exerting anti-inflammatory effects in ischaemic stroke and other neurological disorders." (PMID 37511539, 2023). "The recognition of LPS patterns by TLR4 plays a critical role in the development of neurological disease." (PMID 37511539, 2023). "Particularly, TLR4 participates in the initiation of neuroinflammation in various neurological diseases." (PMID 36362220, 2022). "Toll‐like receptor 4 (TLR4) participates in the initiation of neuroinflammation in various neurological diseases, including central nervous system injuries." (PMID 35692100, 2022). "miR-132 was related to Toll-like receptor 4 (TLR4), regulated astrocyte activation, and modulated innate immune response in neurological diseases." (PMID 30691440, 2019). "Immunoglobulin A nephropathy (IgAN) is another neurological disease that TLR-4 has an important role in, in which by TLR-4-related induction of proinflammatory cytokines it further results in the development of IgAN." (PMID 31011554, 2019). "Studies of other neurological disease models have shown that TLR4 plays an important role in the pathogenesis of a variety of neuro-inflammation and is expressed in microglia and neurons." (PMID 29311802, 2017). "Disruption of LPS, which is an agonist of TLR4 and interacts with it during TLR4-mediated endocytosis, may inhibit the occurrence of inflammatory reactions, thereby alleviating or treating various neurological diseases." (PMID 36523959, 2022). "Therefore, there exists an intricate association between TLR4 and NLRP3 in the regulation of microglial activation and in providing a potential neuroprotective or neurodegenerative effect in neurological disease." (PMID 36362220, 2022).
neurological disorders (continued). "TLR4/NF-kB signal pathway is involved in the regulation of multiple important physiological and pathological processes, such as immunity, inflammation, tumorigenesis, aging, and neurological diseases." (PMID 35199645, 2022). "Several studies have suggested that natural compounds targeting TLR4 and microglia may be developed into effective drugs or preventive strategies for the treatment of neurological diseases." (PMID 35370734, 2022). "In addition, MMP-9 is upregulated in a number of neurologic diseases, which can be mediated by TLR4." (PMID 33487119, 2021). "Feeding TLR ligands to GF mice suggests that these microbial products are sufficient to decrease neurologic disease, and our results show that TLR4 exposure may play a more prominent role than TLR2 signaling in this process." (PMID 31309928, 2019). "TLR4 signaling protects from JHMV-induced neurologic disease." (PMID 31309928, 2019). "Microglial-specific TLR4 signaling protects from neurologic disease." (PMID 31309928, 2019). "In several diseases with microbial (gram-negative infections) or nonmicrobial etiology (ischemia/reperfusion injury and neurodegenerative and neurological diseases) there is an involvement of TLR4 activation that, under certain circumstances, can contribute to disease progression." (PMID 27293318, 2016). "Likewise, TLR3−/− mice infected with JEV showed more rapid signs of neurological disorder starting from 3 days pi, whereas TLR4−/− mice showed delayed signs of neurological disorder with a lower frequency of occurrence, compared to wild-type mice." (PMID 25188232, 2014). "In addition, the modulatory effects of canagliflozin on toll-like receptor 4/NLRP3 inflammasome signalling might potentiate its anti-inflammatory effects in various neurological disorders." (PMID 39596990, 2024). "Authors were also demonstrated in TLR4-KO mice, in which they found the similar gut and neurological disorders that could be reversed/reduced by rotenone treatment, suggesting that the TLR4-induced inflammatory signaling plays vital role in gut and brain inflammation in PD." (PMID 33066156, 2020). "Therefore, we aimed to determine whether each TLR signal pathway modulated neurological disease caused by JEV infection, using several TLR-deficient mice (TLR2, TLR3, TLR4, TLR7, TLR9)." (PMID 25188232, 2014). "They attenuate inflammation-induced disorders such as cardiovascular and neurological disorders via down-regulating pro-inflammatory cytokines (IL-6, CRP, COX-2, LPO, TGF-β1, NF-κB, and TNF-α), and pathways (IRAK4, MAPK, JAK/STAT3, TLR4, and ERK)." (PMID 41640995, 2026). "BV attenuates pro-inflammatory responses and inhibits toll-like receptor 4 (TLR4) signaling by modulating the nuclear factor κB (NF-κB) pathway, a key factor in the pathogenesis of neurological disorders." (PMID 40642384, 2025). "Toll-like-receptor 4 (TLR4) is the main receptor for LPS, which mediates pro-inflammatory signaling in various neurological disorders and glial fibrillary acidic protein (GFAP) is a common marker for astrocyte activation." (PMID 39337602, 2024). "Researchers have highlighted the fact that TLR4 is indispensable for leukocyte recruitment into brain in response to LPS and upregulated expression of CCR5 in neurological diseases is often immunolocalized in microglia." (PMID 26457222, 2015). "Surface expression of TLR4 and CD14 in microglia has been shown to be elevated in various neurological disorders like ALS and AD." (PMID 23234315, 2012). "We have shown previously that inactivation of the TLR4-MyD88 pathway in MPS IIIB mice suppressed early-onset neuroinflammation but did not prevent neurologic disease." (PMID 39497064, 2024). "Furthermore, BV alleviates pro-inflammatory responses through the NF-κB pathway and inhibits toll-like receptor 4 (TLR4) signaling, which is the main contributor to neurological disorders." (PMID 35624787, 2022).
neurological disorders (continued). "This review summarises the anti-neuroinflammatory activities of CBD against various neurological disorders with a particular focus on their main molecular mechanisms of action, which were related to the downregulation of NADPH oxidase-mediated ROS, TLR4-NFκB and IFN-β-JAK-STAT pathways." (PMID 35956911, 2022). "Acupuncture treats nervous system diseases by increasing the brain-derived neurotrophic factor level and involves multiple signal pathways, including p38 MAPKs, Raf/MAPK/ERK 1/2, TLR4/ERK, PI3K/AKT, AC/cAMP/PKA, ASK1-JNK/p38, and downstream CREB, JNK, m-TOR, NF-κB, and Bcl-2/Bax balance." (PMID 31379957, 2019). "Our study demonstrated that the TLR4/NF-κB signalling pathway was an important signalling cascade involved in BBB integrity and melatonin might be a new candidate as a therapeutic agent for protecting the CNS neurological diseases characterized by a compromised BBB." (PMID 28404943, 2017). "Therefore, we have analyzed the expression pattern of Toll-like receptor 4 and its ligands in brain tissue of canine patients with structural or idiopathic epilepsy in comparison with tissue from laboratory dogs or from owner-kept dogs without neurological diseases." (PMID 31959173, 2020).
kidney disease (48 papers, 2007 to 2026). "Multiple investigations have indicated that TLR4 is implicated in the pathogenesis of kidney disease." (PMID 38287815, 2024). "Previous studies have shown that TLR4 plays a role in inflammatory and fibrotic processes in renal diseases, which are usually associated with activation of the MyD88-NF-κB pathway." (PMID 32388684, 2020). "Toll-like receptor 4 (TLR-4) has been implicated in LPS signaling and is involved in the renal disease induced by expose to bacterial components." (PMID 17617918, 2007). "Although the precise role for chronic inflammation has yet to be clarified in kidney disease, we and others recently revealed the pathogenic role of toll-like receptor 4 (TLR4) in the development and progression of diabetic nephropathy and crescentic glomerulonephritis." (PMID 32080297, 2020). "TLR4 signaling pathway can activate downstream inflammation response signaling pathways such as the NF-κB pathway and result in the release of inflammatory cytokines and chemokines causing inflammation, contributing to the pathogenesis of inflammation-associated renal injury and kidney disease." (PMID 29207635, 2017). "For example, in preclinical animal models, pharmacological targeting of the TLR4 pathway slowed kidney disease progression and found to be kidney protective." (PMID 40059827, 2025). "Collectively, these findings suggest that the TLR4 canonical pathway is activated in kidney diseases." (PMID 38287815, 2024). "Its anti-inflammatory role was supported by a study of murine kidney disease which showed that the upregulation of miR-214 inhibited TLR4 expression and reduced inflammation." (PMID 37474869, 2023). "For example, CHOP deficiency inhibited fibrosis via Hmgb1/TLR4/NFκB signalling through a CHOP-related ERS pathway; ERS caused tubular damage in kidney disease; and irreversible ERS caused kidney cell apoptosis and, consequently, fibrosis." (PMID 36142626, 2022). "The current study investigates the involvement of the TLR4 signaling pathway in ISO-induced nephropathy." (PMID 36474570, 2022). "Inhibition of TLR4 can represent an interesting target to prevent AKI progression into pre-clinical renal diseases." (PMID 36474570, 2022). "Among them, inflammation plays a vital role in the progression of renal diseases, in which toll-like receptor 4 (TLR4) represents a major component in innate immunity." (PMID 32108135, 2020). "The activated TLR4/NF-κB signaling pathway is an important contributor to the inflammatory response in kidney disease." (PMID 29329595, 2018). "The research showed that blocking TLR4 suppressed LPS-induced iNOS expression, and its role in kidney disease is being explored." (PMID 29250558, 2017). "Emerging evidence has indicated that TLR4 was the first identified molecular of TLRs and is positively involved in the development of kidney diseases and DN." (PMID 29207635, 2017). "In a larger context, innate immune signaling has been tied to the pathogenesis of multiple renal diseases and TLR4 signaling, specifically, has been identified as a mediator of diabetic renal disease." (PMID 26990086, 2016). "Among the inflammatory signals, TLR4 signals, which are an innate immune response, reportedly affect the development of various kidney diseases, including DN17." (PMID 27180624, 2016). "Recent studies have demonstrated that kidney disorders are impending in MetS and TLR4 blockade protects kidney in type-2 diabetic mice via modulating the inflammatory signaling." (PMID 25372283, 2014). "This study also suggests that non-pharmacological antioxidant approaches have protective value against MetS-associated CKD and also open up the possibility of a potential target in TLR4 against renal diseases." (PMID 25372283, 2014). "Because TLRs have been implicated as effectors in kidney diseases and TREM-1 has been previously linked to TLR signaling, we investigated TLR-2 and TLR-4 as putative receptors for kidney DAMPs and macrophage activation." (PMID 23844229, 2013).
kidney disease (continued). "To explore this possibility further, we studied the progression of two models of kidney disease in mice deficient in TLR-2, TLR-4 and MyD88." (PMID 23844229, 2013). "Furthermore, certain vitamin D DEGs associated with inflammation, such as TLR4 and TNFRSF11B, showed a significant upregulation with the progression of kidney disease." (PMID 38978780, 2024). "So, HMGB1/TLR4/NF-κB is an important inflammatory signal pathway in renal disorders." (PMID 37498374, 2024). "In kidney disease, TLR4 is highly expressed in the renal tissues of IgAN patients, and may be involved in damage to murine mesangial cells by promoting the production of pro-inflammatory factors." (PMID 32388684, 2020). "Therefore, TLR-4 signaling becomes a very important target for the prevention and treatment of kidney disease." (PMID 27180624, 2016). "Further studies are warranted to analyze the role of TLR4-inflammasome axis in different models of renal disease and whether similar pathways operate in human CKD." (PMID 26416975, 2015). "TLR2 and TLR4 are actively involved in the development of kidney diseases in a sterile environment." (PMID 24842252, 2014). "OA demonstrates preventive and therapeutic effects on kidney diseases by modulating various signalling pathways, including NF- κB, STAT, PI3K/AKT, TLR4, and Nrf2/HO-1." (PMID 38816880, 2024). "In addition, the detailed mechanisms of SEMA3A underlying kidney diseases are not fully understood;, there are several possible signaling pathways, involving SEMA3A signaling, such as Rac1/NF-κB p65, JNK and TLR4 signaling, which may regulate inflammation and cell apoptosis." (PMID 37835781, 2023). "Thus, targeting myeloid TLR4 may be a novel therapy for immunologically mediated kidney diseases." (PMID 34568976, 2021). "In a recent study, Stx increased creatinine levels in wild type and MyD88 knockout mice, but not in TLR4 knockout mice, suggesting a crucial role of TLR4 in Stx-induced kidney disease." (PMID 33467524, 2021). "Thus, myeloid TLR4 plays a pivotal role in anti-GBM GN by immunological switching from M1 to M2 and from Th1/Th17 to Treg and targeting myeloid TLR4 may be a novel therapeutic strategy for immune-mediated kidney diseases." (PMID 34568976, 2021).
immune disorders (46 papers, 2009 to 2026). "Before the beginning of the study, many experimental results confirm TLR2 and TLR4 are implicated in the regulation of a variety of inflammatory and immune disorders." (PMID 29348888, 2017). "While the immune mechanism(s) of PAE-induced immune dysfunction are poorly understood, prior studies implicated the involvement of Toll-like receptor 4 (TLR4) and the nucleotide-binding domain, leucine-rich repeat-containing family, pyrin domain-containing 3 (NLRP3) inflammasomes." (PMID 40628342, 2025). "Since endogenous TLR4 ligands have been associated with several inflammatory- and immune-diseases, B. quintana LPS might be a novel therapeutic strategy for TLR4-driven pathologies." (PMID 27670746, 2016). "Preclinical data suggest that melatonin acts through the RORA and TLR4/TRIF pathways, making it a particularly interesting therapeutic target in the context of immune disorders associated with sleep deprivation." (PMID 40724980, 2025). "For instance, melatonin also acts through the RORA and TLR4/TRIF pathways, making it a particularly interesting therapeutic target in the context of immune disorders associated with sleep deprivation." (PMID 40724980, 2025). "Unlike MUC1, IL-22 also regulates MUC13 expression via p38 MAPK activation, a signaling pathway involved in TLR4-mediated cell proliferation and immune dysfunction in IBD." (PMID 37174625, 2023). "TIPE2 improves the PHSML-mediated CD4+T cells dysfunction by regulating TLR2/TLR4 pathway, providing a new intervention target following hemorrhagic shock-induced immune dysfunction." (PMID 35572554, 2022). "LPS binds to surface TLR4 molecules, triggering the secretion of various inflammatory factors, which contribute to the pathophysiology of septic shock and other immune disease." (PMID 24757670, 2014). "Taken together, we propose a novel direct activation pathway of iNKT cells in the presence of TCR signals via endogenous or exogenous ligand-mediated engagement of TLR4 in iNKT cells, which regulates immune diseases by altering IFN-γ and IL-4 production." (PMID 23028952, 2012). "Our group found that in the absence of TLR2, MG could induce inflammation via TLR6 in DF-1 cells, or TLR4 could be activated by HMGB1 to trigger MG-induced immune disorders in avian macrophage cells." (PMID 37238096, 2023). "More importantly, TLR4 could be activated by HMGB1 to trigger immune disorders after TLR2 was silenced." (PMID 36139393, 2022). "Thus, FAME alleviates LPS-induced inflammation by inhibiting the expression of TLR4, indicating the potential suitability for the treatment of immune disorders." (PMID 34439524, 2021). "In addition, the role of GFW on immune disorder was also confirmed by quantitative analysis of TLR-4 related cytokines." (PMID 30674993, 2019). "The results suggested GFW take effect in immune disorder may through down-regulation of activated TLR-4 signaling related cytokine expression in RAW264.7 cells." (PMID 30674993, 2019). "TLR4 is also the key to sterile inflammation and remote organ dysfunction (such as postfracture acute lung injury) and both immunosuppression and hyperinflammation contribute to immune dysfunction." (PMID 26273144, 2015). "However, the overexpression of HSP 60 can activate TLR-4 and potentially stimulate the immune diseases." (PMID 24738046, 2014). "Thus, intestinal dysbiosis may induce immune disorders by activating the natural and acquired immune systems by activating intestinal mucosal TLR4 proteins, triggering inflammation and ultimately leading to IBS-D." (PMID 39749341, 2024). "Therefore, TLR4 is obviously the most suitable indicator of postfracture immune dysfunction." (PMID 26273144, 2015). "The high expression of differentially expressed genes, such as TLR4, CXC-8, PLA2/G7, HBEGF and FABP2, and the overactivation of immune pathways shown by GSEA prove that immune disorders are involved in the onset of NEC." (PMID 38814387, 2025).